SGPL1 (sphingosine-1-phosphate lyase 1)
Description:
Cleaves phosphorylated sphingoid bases (PSBs), such as sphingosine-1-phosphate, into fatty aldehydes and phosphoethanolamine. Elevates stress-induced ceramide production and apoptosis. Required for global lipid homeostasis in liver and cholesterol homeostasis in fibroblasts. Involved in the regulation of pro-inflammatory response and neutrophil trafficking. Modulates neuronal autophagy via phosphoethanolamine production which regulates accumulation of aggregate-prone proteins such as APP (By similarity). Seems to play a role in establishing neuronal contact sites and axonal maintenance (By similarity).
Synonyms: S1PL; SPL; NPHS14; RENI
Tractability: Small molecule: a structure with a bound ligand is known; a high-quality ligand is known. Antibody: UniProt predicts a signal peptide or a membrane-spanning region. PROTAC: ubiquitination databases record sites on it; its protein half-life has been measured; a small molecule that binds it is known.
Target class: Enzyme; Lyase
Gene: Protein-coding gene on chromosome 10 (70,815,905 to 70,958,701, forward strand). Ensembl gene ENSG00000166224.
Subcellular location: Endoplasmic reticulum membrane
Subcellular location (Human Protein Atlas): Endoplasmic reticulum
Pathways (Reactome):
Metabolism: Sphingolipid catabolism
Gene Ontology:
Molecular function: protein binding; sphinganine-1-phosphate aldolase activity; carbon-carbon lyase activity; pyridoxal phosphate binding
Biological process: apoptotic signaling pathway; ceramide metabolic process; fatty acid metabolic process; sphingolipid catabolic process; lipid metabolic process; sphingolipid metabolic process
Cellular component: endoplasmic reticulum; endoplasmic reticulum membrane
Genetic constraint (gnomAD): Loss-of-function variants: 23 observed, 45.92 expected, observed/expected ratio (o/e) 0.5, 90% interval 0.36 to 0.71. The upper end of that interval is the gene's LOEUF score, 0.71, which puts it in group 2 of 6, group 1 being the genes least tolerant of losing a copy. Missense variants: 443 observed, 576.83 expected, observed/expected ratio (o/e) 0.77, 90% interval 0.71 to 0.83. Synonymous variants: 192 observed, 209.88 expected, observed/expected ratio (o/e) 0.91, 90% interval 0.81 to 1.03.
Gene-disease validity (ClinGen):
ClinGen rates the evidence that SGPL1 causes each of these diseases.
nephrotic syndrome 14 (autosomal recessive): Definitive.
Homologues: Orthologues: chimpanzee SGPL1 (99% identical), macaque SGPL1 (99% identical), dog SGPL1 (93% identical), pig SGPL1 (91% identical), rat Sgpl1 (86% identical), mouse Sgpl1 (85% identical), guinea pig SGPL1 (84% identical), tropical clawed frog sgpl1 (65% identical), zebrafish sgpl1 (64% identical), Drosophila melanogaster Sply (46% identical), Caenorhabditis elegans spl-2 (36% identical), Caenorhabditis elegans spl-3 (34% identical). Paralogues in human: GAD2 (17% identical), GAD1 (17% identical), CSAD (16% identical), GADL1 (16% identical), HDC (12% identical), PDXDC1 (11% identical), DDC (10% identical).
Diseases named in the same sentence as SGPL1 in open-access papers:
SGPL1 is named in the same sentence as 127 diseases in open-access papers, as found by Europe PMC text mining. Sharing a sentence is not in itself a finding about the gene and the disease. The quoted sentences say what the papers report.
colon cancer (14 papers, 2016 to 2024). "It seems that a change in SGPL1 expression is associated with the malignancy of already established colon cancer cells." (PMID 37108361, 2023). "Our recent study showed a relative and separate contribution of SGPL1 localization in inflammation and carcinogenesis in the pathophysiology of colitis associated colon cancer." (PMID 34073605, 2021). "Low SGPL1 content is described for several cancer entities such as breast cancer, colon cancer, OSCC and melanoma, which are associated with a poor prognosis." (PMID 31455837, 2020). "Just recently, functional roles of SGPL1 in colitis-associated colon cancer and inflammation have also been observed in Sgpl1 knockout mouse models." (PMID 31801289, 2019). "Thus, we suggested that manipulation of SGPL1 is associated with the malignancy of already established colon cancer cells." (PMID 34073605, 2021). "Previous reports showed that SGPL1 was downregulated in colon cancer tissue, leading to S1P accumulation in neoplastic intestinal tissues." (PMID 37108361, 2023). "In hepatocellular carcinoma (HCC) and colon cancer, the irreversible breakdown of S1P by SGPL1 triggers aberrant S1P signaling, resulting in the suppression of autophagy and the development of cancer." (PMID 37852968, 2023). "During inflammation induced colorectal cancer progression, Ki-67 abundance increased in SGPL1 knockout colon tumors, indicating an increased proliferation rate of cancerous cells." (PMID 34073605, 2021). "While the colon cancer wildtype cells (SGPL1+/+M.) hardly showed any of these G1-phase characteristics during fluorescence microcopy, the majority of SGPL1−/−M.Ex1 cells did assemble numerous large foci." (PMID 34073605, 2021). "As detailed in the current investigation, we were able to demonstrate that SGPL1 knockout contributes to cell cycle arrest in the colon stem cell niche while already established colon cancer cells find escape mechanisms from cellular quiescence." (PMID 34073605, 2021). "In line with the sphingolipid rheostat theory, previous reports showed that SGPL1 was downregulated in colon cancer, leading to S1P accumulation in neoplastic intestinal tissues." (PMID 32630435, 2020). "For example, SGPL1 is downregulated during intestinal tumorigenesis in the ApcMin/+ mouse model and in human colon cancer specimens compared to adjacent uninvolved tissues." (PMID 29718989, 2018). "To answer this question, we measured the cellular content of both ceramides and S1P, along with the expression of proteins involved in the proliferation/apoptosis pathways, and assessed the apoptosis rate of colon cancer cells in which the genes encoding SPHK1 and SGPL1 had been silenced." (PMID 37108361, 2023). "S1P can be also dephosphorylated by S1P phosphatases (SGPP1,2) and phospholipid phosphatases (PLPP1-3), or it can be irreversibly degraded by S1P lyase (SGPL1), which is highly expressed in enterocytes, and which has been found to be downregulated in colon cancer." (PMID 31801289, 2019). "Furthermore, initiation and progression of colon cancer can also be directed by SGPL1 modification." (PMID 34073605, 2021). "High SGPL1 levels in HCC and colon cancer inhibit protective autophagy, thereby promoting cancer development (as described in the Cancer section)." (PMID 37852968, 2023). "Quantification of Ki-67 and PanCytokeratin (PanCK) double-positive cells revealed that more than 90% of the Ki-67 positive cells of non-malformed and tumor-free epithelial tissue were lost in SGPL1 knockout colons compared to wildtype during colon cancer progression." (PMID 34073605, 2021). "However, in contrast to these previous findings, the upregulation of SGPL1 and no increase in S1P levels were recently reported in human colon cancer tissues." (PMID 32630435, 2020).
colorectal cancer (12 papers, 2020 to 2025). A primary or metastatic malignant neoplasm that affects the colon or rectum. "To elucidate this effect in more detail, we generated SGPL1 deficient colorectal cancer cells via CRISPR/Cas9." (PMID 34073605, 2021). "As hnRNPH binds sphingosine-1-phosphate lyase 1 (SGPL1), its overexpression causes the stabilization and upregulation of SGPL1 in colorectal cancer cells, thereby inhibiting apoptosis and promoting tumor progression." (PMID 34888349, 2021). "hnRNP H1 was also demonstrated to promote colorectal cancer progression via the stabilization of mRNA of Sphingosine-1-Phosphate Lyase 1 in vitro." (PMID 37759675, 2023). "RT-PCR analysis of the surgically resected samples showed that SGPL1 mRNA tended to be highly expressed in human colorectal cancer tissues compared with normal mucosa tissues." (PMID 37108361, 2023). "In a previous study, we found that interference of SGPL1 expression levels augmented a partial re-differentiation of colorectal cancer cells towards normal colon epithelial cells." (PMID 34073605, 2021). "The downregulation of hnRNP H1 or SGPL1 dramatically reduced the growth of colorectal cancer in vitro and in vivo, showing SGPL1 to be a novel binding partner and mediator of the tumor-promoting effect of hnRNP H1." (PMID 32630435, 2020). "An RT-PCR analysis of the surgically resected samples in our institution showed that SGPL1 mRNA tended to be highly expressed in colorectal cancer tissues (n = 32) compared with normal mucosa tissues (n = 28) (p-Value = 0.10)." (PMID 32630435, 2020). "The present study showed that hnRNP H1 promoted colorectal cancer cell progression by inhibiting cell apoptosis and by binding to and stabilizing SGPL1 mRNA in colorectal cancer cells." (PMID 32630435, 2020). "Reverse transcription-polymerase chain reaction revealed the high expression of hnRNP H1 mRNA in colorectal cancer cells and Spearman’s rank correlation coefficient showed a strong positive correlation between hnRNP H1 mRNA and SGPL1 mRNA." (PMID 32630435, 2020). "Notably, SGPL1-mediated S1P degradation in hepatocellular and colorectal carcinomas disrupts S1P signaling, suppressing autophagy and accelerating carcinogenesis." (PMID 40906080, 2025). "It has been shown that diminished SGPL1 expression induced a partial redifferentiation of human colorectal cancer cell line towards normal colon epithelial cells, as a result of E-cadherin upregulation, an increase in intercellular adhesion, and inhibited cell migration." (PMID 37108361, 2023). "Moreover, silencing of SGPL1 influences the tumorigenic activity of established colorectal cancer cells and partial redifferentiation of colorectal cancer." (PMID 35565311, 2022). "For instance, we showed that hnRNP H1, which is highly expressed in colorectal cancer tissues, directly binds with and stabilizes 54 apoptosis-related mRNAs, including sphingosine-1-phosphate lyase 1 mRNA, thereby promoting the growth of colorectal cancer cells." (PMID 34830186, 2021). "The aim of our study was to investigate how the modulation of sphingolipid metabolism through the silencing of the genes involved in the formation (SPHK1) and degradation (SGPL1) of sphingosine-1-phosphate would affect the sphingolipid profile and apoptosis of HCT-116 human colorectal cancer cells." (PMID 37108361, 2023). "Our results also showed that S1P expression was not changed, whereas the S1P-cleaved enzyme SGPL1 was upregulated, in colorectal cancer cells." (PMID 32630435, 2020).
colorectal cancer (continued). "An siRNA of hnRNP H1 decreased SGPL1 mRNA expression in colorectal cancer cells, but not in non-tumorous cells." (PMID 32630435, 2020). "The intracellular S1P expression was not changed in hnRNP H1- or SGPL1-downregulated HCT116 cells, suggesting that upregulated SGPL1 did not influence sphingolipid metabolism in colorectal cancer cells." (PMID 32630435, 2020).
nephrotic syndrome (11 papers, 2019 to 2025). A collection of symptoms that include severe edema, proteinuria, and hypoalbuminemia; it is indicative of renal dysfunction. "The constellation of ichthyosis, hearing loss, nephrotic syndrome, and lymphopenia, raised the possibility of a causative SGPL1 variant." (PMID 37377976, 2023). "Two cases of nephrotic syndrome caused by SGPL1 variants were admitted to Tongji Hospital, affiliated with Tongji Medical College of Huazhong University of Science and Technology." (PMID 36873630, 2023). "A total of 31 children with SGPL1 variants causing nephrotic syndrome (including the reported two cases) were identified through a literature review." (PMID 36873630, 2023). "Deletion of SGPL1 in mice and humans causes an increase in S1P and ceramides in tissues, resulting in steroid-resistant nephrotic syndrome with mesangial hypercellularity, glomerular hypertrophy, glomerular fibrosis and diffused mesangial sclerosis." (PMID 35457062, 2022). "While most individuals also have nephrotic syndrome, SGPL1 variants also account for isolated adrenal insufficiency at presentation." (PMID 35904228, 2022). "Since the discovery that mutations in the Sgpl1 gene, coding for S1P lyase (SPL), develop a severe form of steroid-resistant nephrotic syndrome, also classified as nephrotic syndrome type 14 (NPHS14), much attention has been directed to the role of iS1P in podocyte function." (PMID 36834691, 2023). "Summary of reported cases of nephrotic syndrome caused by SGPL1 variants (31 cases)." (PMID 36873630, 2023). "Importantly, a genetic mutation in SGPL1 was found in patients with nephrotic syndrome, and mice with SGPL1 deficiency were shown to exhibit severe podocyte injury and proteinuria." (PMID 35457062, 2022). "In humans, sphingosine-1-phosphate lyase (SGPL1) deficiency has been linked to nephrotic syndrome." (PMID 34722589, 2021). "We report two novel likely pathogenic variants in SGPL1 and STAT1 that, in combination, led to increased propensity for opportunistic infections in a patient with additional features of hearing loss, nephrotic syndrome and ichthyosis." (PMID 37377976, 2023). "Mutations in the gene coding for sphingosine-1-phosphate lyase (SGPL1), the enzyme that hydrolyzes S1P irreversibly, results in the SGPL1 insufficiency syndrome (SPLIS), a multi-systemic disorder with incorporation of steroid-resistant nephrotic syndrome and primary adrenal insufficiency." (PMID 40042667, 2025).
Adrenal insufficiency (10 papers, 2017 to 2026). Insufficient production of steroid hormones (primarily cortisol) by the adrenal glands. "The third patient, diagnosed with SGPL-1 deficiency, also suffered from chronic renal and adrenal insufficiency, which contributed to a complicated clinical course." (PMID 41288825, 2025). "Recently mutations in sphingosine-1-phosphate lyase (SGPL1) have been linked to adrenal insufficiency with treatment resistant nephrotic syndrome, dubbed sphingosine phosphate lyase insufficiency syndrome (SPLIS)." (PMID 36674647, 2023). "Compromised development of the X-zone is seen in other mouse models of adrenal insufficiency, including those with Sf1 mutations, suggesting that SGPL1 may also have a role to play in the developing human adrenal." (PMID 28165343, 2017). "We infer from these findings that Sgpl1-KO mice exhibit adrenal insufficiency of unclear origin with reactive upregulation of cortical gene expression." (PMID 33755599, 2021). "Recently, we identified a complex syndrome comprised of nephrosis, adrenal insufficiency, and immunological defects caused by inherited mutations in human SGPL1, the gene encoding SPL." (PMID 29333002, 2017). "SGPL1 mutations were associated with SRNS and facultative ichthyosis, adrenal insufficiency, immunodeficiency, and neurological defects." (PMID 29333002, 2017). "Thus, Sgpl1-KO mice exhibit adrenal insufficiency, which appears refractory to treatment." (PMID 33755599, 2021).
lymphopenia (10 papers, 2009 to 2024). Reduction in the number of lymphocytes. "The major relevance of S1P lyase for various physiological processes is fully supported by the phenotype of Sgpl1-deficient mice, which not only display lymphopenia, but also histological abnormalities in different organs and a markedly reduced life span." (PMID 31314788, 2019). "This activity may aggravate SPLIS lymphopenia, as murine studies have shown that ceramide accumulates in Sgpl1 knockout mouse thymii, causing T cell apoptosis." (PMID 39454238, 2024). "Overall, our results demonstrate that untreated mice have low but detectable amounts of anti-AAV9 antibody and that Sgpl1-KO mice have a functional immune response to the AAV vector in spite of their lymphopenia." (PMID 33755599, 2021). "Peripheral blood counts in Sgpl1-KO mice revealed absolute lymphopenia and anemia as shown by low hemoglobin, hematocrit, and RBC mass compared with WT." (PMID 33755599, 2021). "Since mice with global Sgpl1 knockout showed lymphopenia and neutrophilia, blood cell counts were evaluated." (PMID 34638955, 2021). "SGPL1 disruption in T cells resulted in modest accumulation of T cells in the thymus and an increase in thymic S1P levels but did not phenocopy the severe thymic egress defect and peripheral lymphopenia observed in SPLMx1KO mice." (PMID 29333002, 2017). "These long-term effects are probably underestimated in studies where, e.g., short-term experimental metastasis models are not affected by lymphopenia upon SPNS2 ablation or SGPL1 inhibition." (PMID 35163211, 2022). "However, the one phenotype that was not corrected using AAV9 to deliver a working copy of the SGPL1 gene was lymphopenia." (PMID 39454238, 2024). "Interestingly, in our previous study, AAV-SPL did not impact the lymphopenia of Sgpl1 KO mice; thus, our findings reveal an important benefit of AAV-SPL 2.0." (PMID 37958544, 2023).
primary adrenal insufficiency (8 papers, 2018 to 2025). A hormonal disorder that occurs when the adrenal glands fail to release adequate amounts of glucocorticoids (cortisol), mineralocorticoids (aldosterone, 11-deoxycorticosterone), and androgens (dehydroepiandrosterone) to meet physiologic needs, despite release of ACTH from the pituitary. "In 2017, several groups reported biallelic SGPL1 variants in association with SPLIS - a multi-systemic disease including primary adrenal insufficiency, ichthyosis, and steroid resistant nephrotic syndrome." (PMID 37377976, 2023).
colitis (7 papers, 2016 to 2023). Inflammation of the colon. "We found previously that gut-specific disruption of murine Sgpl1 results in sensitivity to colitis due to Stat3 activation." (PMID 33755599, 2021). "A SGPL1 knockout in the immune cell compartment augmented immune cell infiltration, initiating colitis with lesions and subsequent pathological crypt remodeling." (PMID 34073605, 2021).
Immunodeficiency (6 papers, 2017 to 2023). Failure of the immune system to protect the body adequately from infection, due to the absence or insufficiency of some component process or substance. "As such, SPL modulation has pleiotropic effects, and mutations in human SGPL1 are associated with a variety of disease states including but not limited to immunodeficiency." (PMID 29333002, 2017). "Herein, we describe a newborn with novel homozygous variants in both SGPL1 and STAT1 presenting with severe combined immune deficiency and additional clinical features." (PMID 37377976, 2023). "Next generation sequencing with a primary immune deficiency (PID) gene panel, including SGPL1, was initiated." (PMID 37377976, 2023). "We report novel homozygous SGPL1 and STAT1 variants in a newborn of Gambian ethnicity with clinical features of SPLIS and severe combined immunodeficiency." (PMID 37377976, 2023).